RNU6-988P (RNA, U6 small nuclear 988, pseudogene)
Gene: Small nuclear RNA gene on chromosome 8 (38,122,374 to 38,122,480, forward strand). Ensembl gene ENSG00000253437.
Homologues: Orthologues: chimpanzee U6 (96% identical), macaque U6 (93% identical). Paralogues in human: RNU6-19P (86% identical), RNU6-1060P (85% identical), RNU6-12P (85% identical), RNU6-13P (85% identical), RNU6-31P (85% identical), RNU6-32P (85% identical), RNU6-480P (85% identical), RNU6-536P (85% identical), RNU6-949P (85% identical), RNU6-1 (84% identical), RNU6-15P (84% identical), RNU6-17P (84% identical), and 1286 more.